ALB (albumin)
Diseases named in the same sentence as ALB in open-access papers (continued):
Sharing a sentence is not in itself a finding about the gene and the disease.
polycythemia (5 papers, 2018 to 2025). Abnormally high mass or concentration of red blood cells in the blood, either due to an increase in erythropoiesis or a decrease in plasma volume. "High pelvic 99mTc-albumin fixation was shown to discern 19 PV patients from those with secondary polycythemia." (PMID 33879266, 2021). "Lastly, one study performed 99mTc-albumin scintigraphy in 37 patients with polycythemia." (PMID 33879266, 2021). "Following numerous investigations that eliminated causes of true polycythemia, the presence of reduced total body water, and hence relative polycythemia, was confirmed using radioisotope-labeled red blood cells and albumin-labeled plasma, as well as bioimpedance spectroscopy." (PMID 30587223, 2018). "Furthermore, in our study, patients with polycythemia were younger, had a better nutritional status (higher BMI and albumin), lower inflammatory markers (CRP, PCT, G test, GM test), which might also be one of the reasons why they had a lower risk of adverse outcomes." (PMID 41179861, 2025). "A subgroup analysis based on a paraneoplastic syndrome revealed significant differences in patients with erythrocytosis compared to those without paraneoplastic syndromes in terms of tumor size, albumin, and AFP levels (p < 0.001)." (PMID 38674198, 2024).
prostate tumors (5 papers, 2008 to 2024). "Recent studies using mouse xenografts have shown that a testosterone-albumin conjugate (testosterone-BSA) induced potent apoptotic regression of prostate tumors in vivo." (PMID 19948074, 2009). "Furthermore, it has been proposed that specific mAR-activating ligands, namely testosterone-serum albumin conjugates, may be developed as novel drug candidates for the treatment of mAR+ prostate tumors." (PMID 19055752, 2008).
pulmonary congestion (5 papers, 2015 to 2024). "She received IV albumin from admission days 5 to 6 and enteral cilostazol from admission days 5 to 18; she could only tolerate two days of albumin due to pulmonary congestion." (PMID 39553040, 2024). "Daily volume status should be carefully assessed (hypoxia, jugular venous distention, pulmonary vascular congestion on chest radiography, elevated right ventricular systolic pressure on echocardiography), especially in the setting of concurrent albumin administration." (PMID 38202206, 2023). "On admission, this cluster was represented by the highest proportion of patients presenting with the most severe pulmonary congestion and lowest WBC, ferritin, TSAT, urine Na+, lactates and highest troponin, INR and albumin in the laboratory measurements." (PMID 35884819, 2022).
resistant hypertension (5 papers, 2014 to 2024). "Prognostic impact of baseline urinary albumin excretion rate in patients with resistant hypertension: a prospective cohort study." (PMID 32267335, 2020).
retinal detachment (5 papers, 2011 to 2022). An eye emergency condition which may lead to blindness if left untreated. "This dose of albumin was chosen following previous experiments and measurement of albumin concentrations in the subretinal fluid of patients with retinal detachment, in order to mimic a realistic clinical condition." (PMID 35337132, 2022). "Protein spots that were upregulated in the vitreous following retinal detachment were identified as albumin fragments, and those downregulated were found to be peroxiredoxin 2, collagen-Iα1 fragment, and α-1-antiproteinase F. Conclusions." (PMID 26664739, 2015). "Analysis with 2D-PAGE revealed fragments of albumin to be upregulated in the vitreous following retinal detachment." (PMID 26664739, 2015). "Three 2D-gel spots identified as fragments of albumin were found to increase with retinal detachment." (PMID 22065916, 2011). "In this study, we bring evidence that both UDCA and TUDCA protected the retina from albumin-induced cell death, including apoptosis and necroptosis, in a model of retinal detachment, confirming results previously published using oral UDCA in retinal detachment." (PMID 35337132, 2022). "The amount of the Eno1, vimentin, albumin and prohibitin was increased, while the amount of tubulin β‐2C, fructose‐bisphosphate aldolase A and other proteins was reduced in the retina of animals after retinal detachment." (PMID 28781956, 2017). "When ocular barriers are disrupted by pathological processes (retinal detachment, inflammation, glaucoma, trauma, or diabetes), the albumin concentration increases inside the ocular media and tissues and could contribute to photoreceptor cell death, as shown in neurons." (PMID 35337132, 2022). "Indeed, pathological subretinal fluid following retinal detachment has a very different protein composition from normal IPM, containing significant amounts of serum proteins such as albumin, transferrin, and gammaglobulin subunits." (PMID 22065916, 2011).
systemic sclerosis (5 papers, 2021 to 2025). A chronic disorder, possibly autoimmune, marked by excessive production of collagen which results in hardening and thickening of body tissues. "In patients with systemic sclerosis, low pre-albumin levels were often accompanied by reduced handgrip strength and fat-free mass, highlighting its potential utility in muscle function assessment." (PMID 40697555, 2025).
thalassemia (5 papers, 2019 to 2025). An inherited blood disorder characterized by a decreased synthesis of one of the polypeptide chains that form hemoglobin. "For coping with oxidative stress, nonenzymatic defense mechanisms encompassing metal-binding proteins (such as haptoglobin and albumin) and free radical scavengers like serum UA are required to maintain redox homeostasis, which is disturbed in diseases affecting iron metabolism, such as thalassemia." (PMID 38255787, 2024). "Regarding α-thalassemia, during HU therapy the children without α-thalassemia had elevated hemoglobin, hematocrit, MCV, MCH, glucose, HDL-C and albumin levels, in addition to decreased MCHC and AST, as well as WBC, neutrophils, eosinophils, lymphocytes and reticulocytes (p<0.05)." (PMID 31306416, 2019). "Children with α-thalassemia presented decreased ALT during HU use, while those without this deletion presented increases in hemoglobin, hematocrit, MCV, MCH, HDL-C and albumin, as well as decreases in MCHC, neutrophils, lymphocytes, reticulocytes and AST (p<0.05)." (PMID 31306416, 2019).
thrombotic disease (5 papers, 2020 to 2023). The formation of a blood clot in the lumen of a vessel or heart chamber; causes include coagulation disorders and vascular endothelial injury. "A high ratio of fibrinogen to albumin accelerates erythrocyte aggregation in capillaries, which is also a cause of the occurrence of thrombotic disease." (PMID 34966791, 2021). "The role of LDH and albumin in the development of thrombotic disorders warrants further investigation." (PMID 37462901, 2023). "In addition, several studies have shown that serum ALB has a predictive value for a variety of thrombotic diseases." (PMID 32695227, 2020).
Ureteral obstruction (5 papers, 2017 to 2024). Obstruction of the flow of urine through the ureter. "Similar findings were also demonstrated in several rat or mice models treated with NX, adenine, unilateral ureteral obstruction and cationic bovine serum albumin (CBSA)." (PMID 39239643, 2024).
Ventricular arrhythmia (5 papers, 2022 to 2025). "A low albumin level is associated with inflammation, and impaired synthetic function of liver and this has been linked to diastolic dysfunction in humans which indicate the association between inflammation and ventricular arrhythmias." (PMID 35706565, 2022). "Burst pacing on an RVOT tissue strip could not induce ventricular arrhythmia at baseline or after bovine serum albumin treatment." (PMID 36325589, 2022).
alopecia (4 papers, 2017 to 2025). Hair loss usually from the scalp. "Specifically, the estimated genetic correlation between BMD and height, blood protein levels (albumin) and hair/balding pattern 3 (moderate hair loss) or 4 (severe hair loss) was significant (P value < 0.05) and positive." (PMID 32637184, 2020). "Univariate analysis revealed significant differences in albumin (ALB) levels (p = 0.037), creatinine (CREA) levels (p = 0.002), nausea occurrence (p = 0.008), vomiting occurrence (p = 0.013), rashes occurrence (p = 0.002), and chemotherapy-induced alopecia incidence (CIA) (p = 0.002)." (PMID 40417218, 2025).
Alport syndrome (4 papers, 2019 to 2025). A rare renal disease characterized by glomerular nephropathy with hematuria progressing to end-stage renal disease (ESRD), frequently associated with sensorineural deafness, and occasionally with ocular anomalies. "Three lines of urinary podocytes obtained from nephrotic patients’ urine and a line of Alport syndrome patient podocytes were characterized and used to assess albumin permeability in response to nKPC-EVs or various drugs." (PMID 39143486, 2024). "Further experimental evidence on the tubular toxicity of filtered albumin came from the generation of a mouse model of Alport syndrome knockout for albumin." (PMID 39529801, 2024). "Additional signals include restoration of nephrin/podocin and α-Klotho, protection of actin cytoskeleton and podocyte density in a nondiabetic proteinuric model, reduced podocyte lipotoxicity in Alport syndrome, and decreased urinary albumin with a related SGLT2 inhibitor." (PMID 41009556, 2025).
Arterial thrombosis (4 papers, 2020 to 2024). The formation of a blood clot inside an artery. "It is speculated that lower concentrations of anticoagulant proteins and serum albumin (particularly < 20 g/L) are obvious risk factors for arterial thrombosis secondary to NS." (PMID 37884862, 2023). "However, arterial thrombosis still occurs in some NS patients with serum albumin levels greater than 30 g/L." (PMID 37884862, 2023). "Finally, the albumin levels were lower in the subjects treated only with BAT than in the other group, anyway, according to previous studies, only when albumin is below a specific range—i.e., <35g/L—the risks of venous and arterial thrombosis increase." (PMID 33505983, 2020).
autonomic dysfunction (4 papers, 2022 to 2025). "In univariate analysis, Medical Research council sum score (MRC) on admission (p < 0.001), bulbar paralysis (p < 0.001), autonomic dysfunction (p < 0.001), HBcAb (p = 0.009), neutrophil/lymphocyte ratio (NLR) (p < 0.001), and Serum albumin (p = 0.016) were associated with MV." (PMID 40066308, 2025). "The results showed that autonomic dysfunction, consciousness declination, ICU admission, WBC, CRP, neutrophil percentage, albumin, and NPAR were statistically significantly different between the two groups (P < 0.05)." (PMID 35479085, 2022). "On the ninth day after initial symptoms, the patient presented sensory and motor nerve disturbances with the cerebrospinal fluid analysis showing a clear albumin-cytologic dissociation, consistent with an atypical presentation of GBS with autonomic dysfunction." (PMID 35317762, 2022). "Compared with the non-MV group, patients in the MV group had more common bulbar paralysis, autonomic dysfunction, HBcAb positivity, higher NLR, but lower MRC and serum albumin, while the rest of the indices were not statistically different between the two groups." (PMID 40066308, 2025).
Brain atrophy (4 papers, 2011 to 2024). Partial or complete wasting (loss) of brain tissue that was once present. "However, other authors suggest that increased albumin levels at disease onset are associated with increased brain atrophy and disability following the onset of MS." (PMID 39337497, 2024). "By multivariate linear regression analysis we demonstrated that the 24S-OH-Chol/TC ratio was significantly correlated with hs.CRP independent of age, albumin levels, brain atrophy, Babcock test, and FAB score (ANOVA: p:0.04; r2: 0.104)." (PMID 21970714, 2011).
bronchitis (4 papers, 2011 to 2025). An acute or chronic inflammatory process affecting the bronchi. "Redo surgical operations and infectious complications are the major risk factors for abdominal wound dehiscence, but also presence of low albumin, glucocorticoid use, chest infections, and emergency surgeries have been also implicated." (PMID 40171449, 2025). "In the present study, the sections of the lung tissues of animals sensitized with egg albumin depicted marked bronchitis and severe bronchoconstriction." (PMID 21607053, 2011).
cardioembolic stroke (4 papers, 2013 to 2025). "Patients with cardioembolic stroke had significantly higher levels of NT-proBNP and lower globulin/albumin (G/A) ratio compared with the other subgroups." (PMID 24734185, 2014). "Since in the clinical practice the diagnosis of cardioembolic stroke is strongly related to the presence of AF, we repeated the analysis after excluding it, and results for BNP levels, NIHSS score, and globulin/albumin ratio were even stronger." (PMID 24734185, 2014).
cerebral oedema (4 papers, 2019 to 2024). "We conclude that the consumption of M. oleifera fortified finger millet porridge was effective in improving the serum albumin and retinol status of the children with cerebral palsy as well as their weight status." (PMID 36962678, 2022). "Furthermore, children with cerebral palsy have been demonstrate to have reduced levels of protein metabolism indices (albumin, creatinine, and uric acid) compared to controls, being enterally-fed children more at risk than oral-fed children." (PMID 39224181, 2024).
chlamydial infection (4 papers, 2012 to 2025). "We collected data on chlamydia and three biomarkers including monocyte, neutrophils, and albumin from six consecutive and independent surveys of NHANES (1999–2000, 2001–2002, 2003–2004, 2005–2006, 2007–2008, 2009–2010)." (PMID 39375883, 2024). "Analysis of the chlamydia data: estimates (Est) and variances (Var) of AUC for the three individual biomarker (monocyte, neutrophils and albumin) and their best linear combination based on individual (J=1) and group testing (J=2,5) approaches." (PMID 39375883, 2024). "Plasma albumin followed the pattern of weight gains and was highly significantly reduced at high chlamydial infection intensity." (PMID 23024776, 2012). "Our interpretation of the positive anti-chlamydial antibody contribution combined with the positive albumin contribution was that this reflected immune protection following chlamydial infection that improved liver function." (PMID 23024776, 2012). "Again, IGF-1 completely followed the pattern of body weight gains and plasma albumin, and the reverse patterns of chlamydial infection intensity, conjunctival inflammation, and plasma globulin." (PMID 23024776, 2012). "Comparison of the clusters unambiguously showed that high chlamydial infection intensity highly significantly co-segregated with high plasma globulin and low albumin, IGF-1, and body weight gain." (PMID 23024776, 2012). "Levels of the negative APP albumin dropped after onset of chlamydial infection in all animals." (PMID 26209015, 2015). "We interpreted the strong contribution of anti-chlamydial IgM to PC 1, as well as the negative albumin and positive globulin contribution, as an indicator of the inflammation driven by chlamydial infection, and therefore termed PC 1 “Chlamydial Inflammation Index”." (PMID 23024776, 2012).
cholelithiasis (4 papers, 2012 to 2024). The presence of crystallized deposits forming in the gallbladder or biliary tree, primarily composed of cholesterol, bilirubin, and bile. "Among all the characteristics, age, cholelithiasis, RR, SBP, DBP, SOFA, platelet, total bilirubin, serum calcium, creatinine, albumin, prothrombin time, activated partial thromboplastin time, and arterial pH differed significantly between the two groups (P < 0.05)." (PMID 38977953, 2024).
clostridium difficile infection (4 papers, 2020 to 2021). Symptomatic infection due to the spore-forming bacterium clostridium difficile. "This found that both serum albumin and ATLAS were predictors of disease complications and mortality from Clostridium difficile infection while only serum albumin was significantly associated with 90-day disease recurrence." (PMID 33925831, 2021). "Several potential risk factors for AAD or Clostridium difficile infection have been reported, including low ADL, tube feeding, low serum albumin, and renal disease." (PMID 34001039, 2021). "The strongest statistically significant positive predictor of readmission was Clostridium difficile infection in the 30-day model and Albumin < 2 g/dL in the 7-day model." (PMID 32933505, 2020).
colon adenocarcinoma (4 papers, 1998 to 2020). "In the colon adenocarcinoma LS174T with a spherically symmetrical distribution of Evans blue-albumin, the median hydraulic conductivity in vivo and after circulatory arrest at a flow rate of 0.1 microl min(-1) was, respectively, 1.7x10(-7) and 2.3x10(-7) cm2 mmHg(-1) s." (PMID 9836476, 1998).
colorectal polyps (4 papers, 2018 to 2024). "In our study, decreased albumin was found to be associated with the development of colorectal polyps." (PMID 32332839, 2020). "Regular cigarette smoking and albumin were independent risk factors for the development of colorectal polyps." (PMID 32332839, 2020). "All covariables were significantly associated with the presence of colorectal polyps, except albumin." (PMID 30359431, 2018). "However, the specific association between albumin and the development of colorectal polyps remains to be further studied." (PMID 32332839, 2020). "While in the multivariate models, regular cigarette smoking (adjusted hazard ratio [AHR] 1.842; 95% CI 1.139–2.980; P = 0.013) and lower albumin (AHR 0.901; 95% CI 0.819–0.991; P = 0.032) were the independent risk factors for the development of colorectal polyps." (PMID 32332839, 2020). "Besides, the subjects with colorectal polyps had lower TC, albumin, and ESR." (PMID 32332839, 2020).
colorectal tumor (4 papers, 2013 to 2025). "Similarly, in patients with relapsed or unresectable colorectal tumors, low albumin concentrations correlated with shorter total survival (OS)." (PMID 29019951, 2017). "Interestingly, the albumin-targeted complex Ox-MSA-Mal significantly inhibited colorectal tumor growth via the i.v. route, while the non-targeted Ox-MSA-PEG-Ca failed to do so." (PMID 40191696, 2025).
congenital heart disease (4 papers, 2015 to 2025). A heart disease that is present at birth. "Our study underscores the critical role of albumin levels and urine output in the postoperative management of pediatric patients undergoing cardiac surgery for congenital heart disease." (PMID 39768386, 2024).
cystinosis (4 papers, 2018 to 2025). Cystinosis is a metabolic disease characterized by an accumulation of cystine inside the lysosomes, causing damage in different organs and tissues, particularly in the kidneys and eyes. "Surprisingly, while both cystinosin and cystinosinLKG interacted with NHE3, rescue of the expression of CTNS, but not CTNS-LKG, was able to restore normal trafficking of NHE3 in cystinosis patient PTCs and improve sodium and albumin uptake in CTNS-deficient PTC lines." (PMID 39990449, 2025). "Conversely, CTSB-dependent albumin catabolism promotes glutathione synthesis by exporting cystine from lysosomes via the transporter cystinosis fuels, thereby inhibiting lethal lipid peroxidation." (PMID 40895546, 2025). "In turn, these changes inhibited the nuclear translocation of ZONAB and restored the differentiation and endocytic uptake of albumin in cystinosis cells." (PMID 29323117, 2018). "We demonstrated that, while no uptake of albumin was observed in the undifferentiated Cys-uKPC (Cys-uKPC #1), effective endocytosis of albumin was present in Cys-uKPC-Podo (Cys-uKPC #1-Podo), comparable with a conditionally immortalized cystinosis podocyte (ciPodocyteCTNS−/−)." (PMID 35406807, 2022).